EPO (erythropoietin)
Diseases named in the same sentence as EPO in open-access papers (continued):
Sharing a sentence is not in itself a finding about the gene and the disease.
hemangioblastoma (11 papers, 2009 to 2024). "To elucidate the pathomechanism, we systematically investigated the relation between polyglobulia, serum EPO level, size of the solid tumor and associated cyst in hemangioblastomas." (PMID 30214643, 2018). "We prospectively evaluated hemoglobin and EPO levels in a series of 33 consecutive patients operated on hemangioblastomas in our center." (PMID 30214643, 2018). "According to our own previous research, hematocrit may be high due to tumoral erythropoietin production that may be seen in hemangioblastomas." (PMID 39045559, 2024). "Hemangioblastoma pathogenesis is believed to be secondary to dysregulation of the HIF pathway with inappropriate elevation of HIF-1a leading to increased expression of erythropoietin and vascular endothelial growth factor." (PMID 28388566, 2017). "Both VEGF and erythropoietin (EPO) are upregulated by HIF, and coexpression of VEGF and EPO is observed in CNS-HB hemangioblastomas." (PMID 39850947, 2024). "The oncogenesis of hemangioblastoma is related to the dysregulation of HIF pathway leading to the increase of vascular endothelial growth factor and erythropoietin." (PMID 31649892, 2019). "Notably, VEGF and EPO are HIF-1α targets involved in angiogenesis and oxygen supply to cells, while SOX2 is a transcriptional target of HIF-2α and is a stemness target implicated in the undifferentiated nature of the mesenchymal component predominant in hemangioblastomas." (PMID 26394686, 2015). "In fact, propranolol inhibited HIF-dependent transcription in a 9xHRE HeLa reporter cell line and the crucial gene targets for hemangioblastoma survival, such as VEGF, EPO and SOX2." (PMID 26394686, 2015). "We therefore conclude that the occurrence of polyglobulia in patients with hemangioblastomas does not depend on serum EPO levels." (PMID 30214643, 2018). "Interestingly enough, all the HIF target genes, including among others, VEGF, MMPs, EPO or FGF, are absolutely necessary for the survival and progression of tumors in general, and for hemangioblastomas in particular." (PMID 26394686, 2015). "Considering that hemangioblastomas represent embryonic cells, the produced EPO might be a form of fetal EPO, which is measurable but not functional like its adult form." (PMID 30214643, 2018).
hemoglobinopathies (11 papers, 2012 to 2025). "Specific hematological parameters included the presence of hemoglobinopathies and erythropoietin." (PMID 31792345, 2019).
Hypoglycemia (11 papers, 2013 to 2025). A decreased concentration of glucose in the blood. "Therefore, we sought to understand if and how EPO-associated hypoglycemia can affect adrenal epinephrine release." (PMID 34480587, 2021). "We recently showed in patients with type 1 diabetes that the concentration of EPO increases modestly in response to hypoglycemia and that low baseline EPO levels may be associated with more pronounced cerebral dysfunction during experimental hypoglycemia than higher levels of EPO." (PMID 23577069, 2013). "We first measured blood glucose levels (BGLs) in all mouse lines and found that both erythrocytotic P2H1 and EPO Tg6 mice display significant hypoglycemia, while conversely, the anemic FOXD1:cre-HIF2αf/f mice were dramatically hyperglycemic." (PMID 34480587, 2021). "Recently, it has been shown that hyperactive erythropoiesis, as seen in EPO Tg6 mice, increases systemic glucose consumption and consequent hypoglycemia, which is most probably attributable to a greater number of circulating RBCs." (PMID 34480587, 2021). "In this study we tested if intravenous treatment with EPO ameliorates cognitive dysfunction during hypoglycemia in patients with type 1 diabetes." (PMID 23577069, 2013). "Nine of 11 subjects produced fewer errors during hypoglycemia (compared to baseline) after EPO treatment than after placebo treatment (p = 0.018)." (PMID 23577069, 2013). "In RT2, nine of 11 subjects had a lower reaction time prolongation during hypoglycemia (from baseline) on the EPO day than on the placebo day (p = 0.021, Wilcoxon signed ranks test)." (PMID 23577069, 2013). "The aim of the present study is to test the effects of EPO treatment on cognitive function, hypoglycemic symptoms, counter-regulatory hormonal responses and cortical electrical activity during mild hypoglycemia in patients with type 1 diabetes." (PMID 23577069, 2013). "In a double-blind, randomized, balanced, cross-over study using clamped hypoglycemia they were treated with 40,000 IU of EPO or placebo administered intravenously six days before the two experiments." (PMID 23577069, 2013). "During hypoglycemia, mean plasma glucose concentrations were 2.2 (0.3) mmol/l on the EPO day and 2.0 (0.3) mmol/l on the placebo day (p = 0.043)." (PMID 23577069, 2013). "We studied if treatment with the neuroprotective hormone erythropoietin (EPO) enhances cognitive function during hypoglycemia." (PMID 23577069, 2013). "Since it is the first of its kind, the determination of timing and dosage of EPO injection in relation to induction of hypoglycemia has been done on an empirical basis supported by only one previous study." (PMID 23577069, 2013). "The mean capillary glucose concentrations (SD) measured bedside during hypoglycemia and used for adjustments of glucose infusion rate were 2.2 (0.1) mmol/l on the EPO day and 2.2 (0.2) mmol/l on the placebo day (p = 0.83, paired t-test)." (PMID 23577069, 2013). "Simultaneous loss of PHD2 in renal erythropoietin (EPO)-producing cells (REPCs) stimulated HIF2α-driven EPO overproduction, excessive RBC formation (erythrocytosis), and systemic hypoglycemia, which is necessary and sufficient to enhance exocytosis of epinephrine from the adrenal medulla." (PMID 34480587, 2021). "Memantine-treated animals received an infusion immediately after 90 min of severe hypoglycemia, while EPO-treated animals received an intraperitoneal dose both 24 h before and after the experimental procedure, as well as an intravenous dose immediately after 90 min of severe hypoglycemia." (PMID 30696060, 2019). "Several studies have reported a possible link between erythropoietin level and hypoglycemia." (PMID 30719249, 2018). "Our study indicates that EPO treatment may enhance some mental processes during hypoglycemia." (PMID 23577069, 2013). "Mechanistically, we show that excessive epinephrine secretion is related to EPO-induced systemic hypoglycemia, rather than a direct cell-level effect of EPO per se." (PMID 34480587, 2021).
Hypoglycemia (continued). "Thus, based on our observations, we suggest, for the first time, that EPO-induced RBC excess, and consequent hypoglycemia, leads to enhanced exocytosis of epinephrine that is mediated by enhanced Ca2+ uptake in chromaffin cells." (PMID 34480587, 2021). "Normoglycemia revealed no significant increase in EPO in either patient group, while hypoglycemia triggered a significant rise in EPO in patients with high RAS activity, but no statistically significant rise in patients with low RAS activity." (PMID 30696060, 2019). "EEG frequency decreased during hypoglycemia, but was not affected by EPO treatment." (PMID 23577069, 2013). "Mechanistically, we propose that the EPO-induced RBC excess and consequent hypoglycemia lead to enhanced exocytosis of epinephrine, irrespective of the primary reduction in adrenal epinephrine synthesis." (PMID 34480587, 2021).
intracerebral hemorrhage (11 papers, 2010 to 2024). A cerebrovascular disorder characterized by bleeding into one or both cerebral hemispheres including the basal ganglia and the cerebral cortex. "Although the probability of occurrence is low, studies have shown a significantly increased risk of serious adverse effects of EPO, including death, intracerebral hemorrhage, brain edema, and thromboembolic events, with high doses and co-administration of tPA." (PMID 39548414, 2024). "Another approach using polylactic-co-glycolic acid nanoparticles of human recombinant erythropoietin decreased the rate of lethal events and improved neurological outcomes when tested in a traumatic intracerebral haemorrhage model." (PMID 35832077, 2022). "In experimental intracerebral hemorrhage, EPO reduction of inflammation and apoptosis was coupled with activation of eNOS, STAT3 and ERK." (PMID 24918289, 2014). "Other data have suggested that EPO treatment in intracerebral hemorrhage induces better functional recovery while reducing perihematomal inflammation and apoptosis via activations of eNOS, STAT3, and ERK." (PMID 22788969, 2012). "This could be related to the ability of EPO to reduce endothelial permeability as recently demonstrated during intracerebral hemorrhages and acute lung injury." (PMID 25352847, 2014). "Moreover, an increased rate of intracerebral haemorrhages was observed after EPO treatment, resulting in an increased mortality in the EPO group." (PMID 20459870, 2010).
neuroblastoma (11 papers, 2007 to 2024). Neuroblastoma (NB) is the most common solid, extracranial childhood tumor. "In addition, activation of AKT by erythropoietin was linked to a resistance against VCR in neuroblastoma cells." (PMID 39408743, 2024). "Intriguingly, mutation of either the distal 5′ or 3′ endogenous HREs completely abolished HIF binding to the proximal EPO promoter HREs as well as to the 3′ HRE in neuroblastoma cells." (PMID 35750861, 2022). "The fact that EPO is produced by some human cell lines derived from neuroblastoma, which mainly originates from the neural crest, provides evidence that the neural crest secretes EPO for primitive erythropoiesis not only in mouse but also in human embryos." (PMID 31245372, 2019). "EPO promotes differentiation towards neurons in several neuroblastoma cell lines, in neural stem cell cultures derived from both embryonic and adult neuronal germinal zones, as well as in embryonic neural progenitor-cell cultures." (PMID 20142991, 2009). "The role of the Stat transcriptional factors in regard to EPO effects in the neural cells remains unclear; EPO induces phosphorylation of Stat5 in neurons, neural stem cells and neuroblastoma cells." (PMID 20142991, 2009). "Although hypoxia-inducible erythropoietin (EPO) gene expression was shown in human neuroblastoma cells, downregulation of Epo mRNA was found in LuM1 aggregates as compared with Colon26 cells, We next examined whether ABCG1 depletion altered HIF-1α levels in tumors." (PMID 30364132, 2018). "Cytokines selected from primary, secondary, and tertiary clusters with respect to EPO (IL-11, KITLG, LIF, THPO) were chosen as experimental candidates, to test their effect on Egr2 mRNA expression in serum-starved EPOR-B104 neuroblastoma cells exactly." (PMID 24672526, 2014). "Notably, the human neuroblastoma cell lines Kelly and SH-SY5Y express the EPO gene in a hypoxia-inducible manner." (PMID 31245372, 2019). "Because neuroblastoma is a common pediatric solid tumor originating from the sympathoadrenal lineage of the neural crest, human embryos are expected to have NEP cells secreting EPO for their primitive erythropoiesis." (PMID 31245372, 2019). "Also in cultures of human neuroblastoma cells (h-NMB), EPO inhibits growth, while it stimulates differentiation." (PMID 27581518, 2016). "Regarding the expression of several neuronal lineage markers in REP cells in vivo, it seemed likely that in human Kelly neuroblastoma cells, known to express Epo in a hypoxia-inducible manner, EPO cis-regulatory elements may be involved which are not active in hepatoma cells." (PMID 35750861, 2022). "Despite its essential function in neuroblastoma cells, neither HIF-2 nor HIF-1 bound the 5′ HRE, but there was an unexpected strong HIF interaction with two newly identified HREs in the promoter region, although the minimal EPO promoter alone showed only a weak hypoxia-inducible activity." (PMID 35750861, 2022).
neuropathy (11 papers, 2009 to 2025). A disorder affecting the nervous system that manifests with pain, tingling, numbness, and/or muscle weakness. "This is corroborated by other studies showing that EPO is neuroprotective in metabolic and toxic models of neuropathy." (PMID 22046448, 2011). "We proved the development of o-Tyr- and/or m-Tyr-induced insulin, acetylcholine, and erythropoietin resistances, which together could lead to abnormal albuminuria and neuropathy and a lower RBC count." (PMID 40227261, 2025). "Further studies are warranted to evaluate the effect of EPO on neuropathy." (PMID 37376074, 2023). "The small peptide ARA290, modeled from the 3-dimensional structure of EPO, has shown efficacy in preclinical models of disease, including neuropathy, without associated adverse effects." (PMID 29392190, 2016). "A cumulative dose of 16 mg cisplatin/kg resulted in clear electrophysiological signs of neuropathy, which were significantly attenuated by concomitant erythropoietin (cisplatin 32,48 m/s ± 1,68 m/s; cisplatin + rhEPO 49,66 m/s ± 1,26 m/s; control 55,01 m/s ± 1,88 m/s; p < 0,001)." (PMID 19602296, 2009). "The pathophysiology of the neuropathy in the POEMS syndrome was associated with the alteration in sodium and potassium channels present in the nodes of Ranvier and axon and the imbalance of increased VEGF (Vascular Endothelial Growth Factors) and decreased serum erythropoietin." (PMID 36999311, 2023).
non-small cell lung carcinoma (11 papers, 2006 to 2024). A group of at least three distinct histological types of lung cancer, including non-small cell squamous cell carcinoma, adenocarcinoma, and large cell carcinoma. "Overexpression of erythropoietin (EPO) and EPO receptor (EPO-R) is associated with poor prognosis in non-small-cell lung carcinoma (NSCLC)." (PMID 31752873, 2019). "Ephrin (EFN)/Erythropoietin-producing human hepatocellular receptors (Eph) signaling has earlier been reported to regulate non-small cell lung cancer (NSCLC) cell survival and cell death as well as invasion and migration." (PMID 33671073, 2021). "On the other hand, it was pointed out that EPO in co-therapy with carboplatin enhances vascularization and perfusion, improves the delivery of carboplatin in non-small cell lung cancer xenografts, and results in more pronounced apoptosis." (PMID 28703764, 2017). "(VEGFR2+) CECs, (CD133+) HPCs, plasma vascular endothelial growth factor (VEGF) and erythropoietin were measured in blood from 25 non-small cell lung cancer (NSCLC) patients before and during treatment with sorafenib plus erlotinib (SO/ER)." (PMID 20010948, 2010). "Non-small cell lung carcinoma (NSCLC) cell line H838 expresses functional EPORs and their treatment with EPO-reduced cisplatin-induced apoptosis." (PMID 34281163, 2021). "The l1 penalty function has previously been applied to an EPO induced JAK2/STAT5 signalling pathway to find cell-type specific behaviour between healthy CFU-E cells and non-small cell lung cancer cells of type H838." (PMID 31311516, 2019). "Functional significance of co-expressed erythropoietin (EPO) and its receptor (EPOR) in non-small cell lung cancer (NSCLC) had been under debate." (PMID 29137269, 2017). "In the meta-analysis, we only conducted the subgroup analyses for non-small cell lung cancer and small cell lung cancer, without fully considering the distribution of tumor subtypes in different studies to evaluate differences in the effects of erythropoietin treatment among different subtypes." (PMID 38967734, 2024).
proliferative diabetic retinopathy (11 papers, 2010 to 2025). Advanced retinopathy due to diabetes mellitus characterized by the formation of new vessels in the retina. "The T allele of rs1617640 has been linked to higher levels of EPO in the vitreous body, suggesting its role in DR pathogenesis, particularly in promoting retinal neovascularization in proliferative diabetic retinopathy." (PMID 41196916, 2025). "One promising discovery, supported by robust statistical and functional evidence, links EPO (erythropoietin) promoter polymorphism to both the presence of proliferative diabetic retinopathy (PDR) and ESRD, as well as EPO expression." (PMID 38542060, 2024). "Elevated erythropoietin concentrations have been linked to proliferative diabetic retinopathy, which in turn is associated with excessive vascular growth." (PMID 31316151, 2019). "High local EPO concentrations in the human vitreous body have been found to be strongly associated with proliferative diabetic retinopathy." (PMID 24782919, 2014). "Human and murine studies have both found that vitreal EPO expression is associated with proliferative diabetic retinopathy." (PMID 22355249, 2012). "The lack of pathological neovascularisation in treatment with epoetin delta is therefore unexpected, especially since it has been demonstrated that raised endogenous EPO levels are associated with proliferative diabetic retinopathy." (PMID 20686695, 2010). "Indeed, EPO was more strongly associated with proliferative diabetic retinopathy than was VEGF." (PMID 20686695, 2010). "In proliferative diabetic retinopathy, locally increased EPO in the vitreous fluid acts independently of the vascular endothelial growth factor (VEGF) to induce retinal angiogenesis." (PMID 36555679, 2022). "During our study, we found that serum erythropoietin concentrations were increased in direct proportion with the severity of the clinical stage of proliferative diabetic retinopathy." (PMID 31727007, 2019). "The highest average value of erythropoietin in serum was found in the group of subjects with the most severe forms of proliferative diabetic retinopathy (9.95 mIU/ml)." (PMID 31727007, 2019). "It has been proved that erythropoietin significantly correlates with the origin of proliferative diabetic retinopathy." (PMID 31727007, 2019). "Erythropoietin is an ischemia-induced angiogenic factor present at increased vitreous levels in patients with proliferative diabetic retinopathy." (PMID 29429414, 2018).
retinopathy of prematurity (11 papers, 2014 to 2025). A bilateral retinopathy characterized by neovascularization, scarring, retinal detachment, and eventually blindness. "Higher day 1 EPO concentrations and 2-week area under the curve were associated with increased risk (p = 0.01) and severity (r = 0.5, p < 0.02) of retinopathy of prematurity." (PMID 34077474, 2021). "In contrast, despite recent promising neuroprotective outcomes of EPO in preterm cohort, routine clinical use of EPO, especially by high-dose, has always been hampered by its risk for retinopathy of prematurity." (PMID 25346720, 2014). "Importantly, EPO use did not increase the incidence of retinopathy of prematurity (ROP), sepsis, or NEC." (PMID 39114855, 2024).
secondary hyperparathyroidism (11 papers, 2014 to 2025). Overproduction of parathyroid hormone in response to influence external to the parathyroid glands. "In conclusion, a combination of EPO and Roxadustat treatment was found to effectively alleviate renal anemia in hemodialysis patients with secondary hyperparathyroidism." (PMID 39151521, 2024). "Secondary hyperparathyroidism is considered an important factor contributing to the degree of bone marrow fibrosis, which impairs the hematopoietic response and requires higher doses of EPO to achieve an adequate hematopoietic effect." (PMID 40244253, 2025). "Moreover, VLPD permitted the reduction of erythropoietin doses of 35% through a better control of phosphate levels and secondary hyperparathyroidism." (PMID 31137545, 2019). "CKD patients often have disturbances in bone and mineral metabolism due to the impairment of renal function, such as secondary hyperparathyroidism, and lack of erythropoietin (EPO) synthesis and Vitamin D." (PMID 30894199, 2019).